VIM (vimentin)
Diseases named in the same sentence as VIM in open-access papers (continued):
Sharing a sentence is not in itself a finding about the gene and the disease.
ischemic stroke (7 papers, 2021 to 2023). A stroke disorder caused by obstruction of blood flow to the brain, due to thrombotic (local blood clot formation) or embolic (due to a blood clot or other material traveling from another site) event. "In summary, we determined that ADM, ANXA3, SLC22A4 and VIM are diagnostic markers of ischaemic stroke." (PMID 35962388, 2022). "In 4,514 patients with carotid plaques in the Malmo Diet and Cancer Cohort, higher plasma levels of vimentin at baseline were associated with the incidence of ischemic stroke after a mean follow-up of 22 years (HR = 1.66, 95% CI: 1.23–2.25)." (PMID 34630291, 2021). "Disruption of this interaction, either with anti-vimentin antibodies or with a von Willebrand Factor fragment, positively affected experimental models of ischemic stroke." (PMID 37356720, 2023). "The mechanism underlying the relationship between ADM, ANXA3, SLC22A4 and VIM and immune cells may be of great significance for the pathogenesis and progression of ischaemic stroke, and related research of these genes could provide new therapeutic insight for ischaemic stroke." (PMID 35962388, 2022). "The expression levels of the ADM, ANXA3, CARD6, CPQ, SLC22A4 and VIM genes were significantly increased in the ischaemic stroke patients compared with those in the healthy subjects (p < 0.05–0.01)." (PMID 35962388, 2022). "The ROC analyses based on the training set, validation set, and our clinical samples showed that the ADM, ANXA3, SLC22A4 and VIM genes remained highly effective in distinguishing the ischaemic stroke patients from the normal subjects." (PMID 35962388, 2022). "Third, more in vivo and in vitro studies are needed to clarify the underlying mechanism of these correlations among ADM, ANXA3, SLC22A4 and VIM and infiltrated immune cells in ischaemic stroke." (PMID 35962388, 2022). "A prospective study showed that there was a significant interaction between carotid atherosclerotic plaque and VIM (vimentin) in the incidence of ischemic stroke." (PMID 34335600, 2021). "Vimentin also has an important role in maintaining plasticity in the nervous system, and several studies have demonstrated that its expression is upregulated after ischemic stroke." (PMID 35722467, 2022). "Therefore, further studies are needed to explore whether therapies targeting these genes such as ADM, ANXA3, SLC22A4 and VIM will bring some similar risks to patients with ischaemic stroke." (PMID 35962388, 2022). "Eight hub genes (ADM, ANXA3, CARD6, CPQ, SLC22A4, UBE2S, VIM and ZFP36) were revealed to be significantly correlated with ischaemic stroke by the LASSO logistic regression and SVM-RFE algorithm." (PMID 35962388, 2022). "Eight hub genes (ADM, ANXA3, CARD6, CPQ, SLC22A4, UBE2S, VIM and ZFP36) were revealed to be significantly correlated with ischaemic stroke by a LASSO logistic regression and SVM-RFE machine learning methods." (PMID 35962388, 2022). "Further verifying the expression levels of these key genes in ischaemic stroke patients, we noticed that the expression levels of ADM, ANXA3, SLC22A4 and VIM were significantly increased in the ischaemic stroke patients compared with those in the normal subjects (p < 0.01)." (PMID 35962388, 2022).
malignant schwannomas (7 papers, 2014 to 2025). "Malignant schwannomas show positive staining for vimentin and CD56 and negative staining for CK, LCA, CD34, SMA, desmin, chromogranin, and synaptophysin." (PMID 25276456, 2014).
medulloblastoma (7 papers, 2010 to 2022). A malignant, invasive embryonal neoplasm arising from the cerebellum. "We detected the expression of EMT markers (E-cadherin and vimentin) in delta-catenin-knockdown medulloblastoma cells and control cells." (PMID 36303547, 2022). "In our data, VIM was observed to be overexpressed in medulloblastoma as compared to controls in accordance with literature." (PMID 34055594, 2021). "Notably, VIM protein was markedly diminished even though its mRNA expression was only slightly reduced in miR-192 overexpressing medulloblastoma cells." (PMID 26506238, 2015). "Functional assays indicated that delta-catenin inhibited medulloblastoma cell invasion and migration through regulating the key factors of EMT pathway, such as E-cadherin and vimentin." (PMID 36303547, 2022). "Next, we transfected the medulloblastoma cells with miR-192 and analyzed EMT-related genes and proteins such as ZEB2, E-cadherin and VIM after miR-192 transfection." (PMID 26506238, 2015). "Furthermore, in vitro invasion assays revealed that medulloblastoma cells overexpressing NICD1 are more invasive in Matrigel chambers and express higher levels of SNAI1 and VIM, which are known to be expressed in metastatic cells." (PMID 30297829, 2018).
oligodendroglioma (7 papers, 2010 to 2025). A well-differentiated (WHO grade II), diffusely infiltrating neuroglial tumor, typically located in the cerebral hemispheres. "This narrative review utilizes a descriptive thematic approach to examine the diagnostic and prognostic utility of vimentin, synaptophysin, and H3K27me as surrogate immunohistochemical markers in differentiating oligodendrogliomas from diffuse midline gliomas (DMGs)." (PMID 40937216, 2025). "Oligodendrogliomas typically lack vimentin expression, while DMGs exhibit moderate to strong vimentin positivity." (PMID 40937216, 2025). "In contrast, oligodendrogliomas usually exhibit low vimentin expression, which can aid in their distinction." (PMID 40937216, 2025). "Eligible literature included peer-reviewed articles focused on the diagnostic, histopathological, immunohistochemical, or molecular characterization of oligodendrogliomas and DMGs, with a specific emphasis on vimentin, synaptophysin, or H3K27me expression." (PMID 40937216, 2025). "In particular, vimentin, synaptophysin, and histone H3 lysine 27 methylation (H3K27me) have gained attention as potential surrogate markers that aid in differentiating oligodendroglioma from DMGs." (PMID 40937216, 2025). "In contrast, oligodendrogliomas usually lack vimentin expression." (PMID 40937216, 2025). "In contrast, oligodendrogliomas typically retain H3K27me3 expression and lack vimentin positivity." (PMID 40937216, 2025). "This revealed high levels of vimentin in GBM, anaplastic astrocytoma (AA) and oligodendroglioma (OD) specimens compared with normal brain controls." (PMID 30987208, 2019). "Oligodendrogliomas typically exhibit low or absent vimentin expression, reflecting their well-differentiated nature and epithelial-like morphology." (PMID 40937216, 2025). "Since a majority of IDHmt tumors are derived from oligodendrogliomas which minimally express vimentin and IDHmt tumors are known to have suppressed angiogenic pathways, differential expression of VEGFR2 and vimentin between IDHmt and IDHwt is not surprising." (PMID 31881020, 2019).
preeclampsia (7 papers, 2014 to 2025). Preeclampsia is a hypertensive disorder of pregnancy that is characterized by new-onset hypertension with proteinuria presenting after 20 weeks of gestation, and depending on mild or severe forms may initially present with severe headache, visual disturbances, and hyperreflexia. "The expression level of Vimentin is positively correlated with cell invasion, especially in epithelial cancers and preeclampsia placenta." (PMID 37038114, 2023). "VIM-AS1promotes preeclampsia via inducing epithelial-to-mesenchymal transition (EMT), with VIM-AS1 supplementation, E-cadherin, Snail, and Vimentin gene and proteins expression levels in the VIM-AS1 group were significantly different compared with that in the Model group." (PMID 40271384, 2025). "Indeed, studies examining placentas from patients with preeclampsia have revealed altered expression profiles of EMT markers, including increased E-cadherin and decreased vimentin expression, indicative of defective EMT." (PMID 40940729, 2025).
solitary fibrous tumor (7 papers, 2012 to 2025). Solitary fibrous tumor (SFT) represents a diverse group of ubiquitous rare spindle cell neoplasms that may be benign or malignant and that most frequently arises from the pleura and peritoneum and rarely from other sites such as head and neck, liver and skeletal muscle. "This characteristic helps distinguish desmoid tumors from other tumors that show fibroblastic proliferation, such as solitary fibrous tumors or nodular fasciitis, which more commonly demonstrate positivity for CD34, vimentin, Bcl-2 and CD99." (PMID 41226994, 2025). "Similar to that in dermatofibrosarcoma protuberans, solitary fibrous tumor commonly labeled with CD34 and vimentin." (PMID 23199263, 2012). "However the immunoprofile of the neoplastic cells was typical of a solitary fibrous tumor (negative for EMA, strongly positive for CD34, vimentin and Bcl-2)." (PMID 22805173, 2012).
adrenal tumor (6 papers, 2005 to 2021). "A panel of markers (CD56, vimentin, melan-A, inhibin-α, synaptophysin, chromogranin and SF-1) are used to establish the origin of adrenal tumors." (PMID 34803919, 2021). "In primary adrenal tumor and gastric metastasis the tumor cells were marked by vimentin, inhibin, synaptophysin, neuron-specific enolase, and calretinin." (PMID 26376405, 2015). "Hedberg and Chen (1986) found that a human adrenal tumor cell line, named SW-13, expressed vimentin filaments and clones derived from these cells were characterized as lacking any detectable cytoplasmic intermediate filaments (vim-)." (PMID 15885136, 2005). "Vimentin was negative for the HCC and adrenal tumor, and Melan-A was also negative for the HCC." (PMID 31696344, 2019).
aneurysm (6 papers, 2016 to 2024). Bulging or ballooning in an area of an artery secondary to arterial wall weakening. "As revealed by immunofluorescence staining, Tsc2 deletion in myeloid cells significantly decreased the expression of contractile SMC phenotype marker sm22α but increased the synthetic phenotype marker vimentin in aneurysm tissues." (PMID 36400753, 2022). "The synthetic phenotype of vSMCs plays a crucial role in progressive aneurysm formation in human and is associated with high expression of VEGF-A, vimentin, KLF-4, and ECM degrading enzymes." (PMID 35563123, 2022). "We also found a direct correlation between senescent and synthetic (vimentin) markers in BAV SMCs, implying that contractile SMCs either switch to the synthetic or senescent phenotype in BAV aneurysms." (PMID 38954721, 2024). "SMCs from aneurysms of the thoracic aorta and from control aortas were analyzed regarding the expression of SMC markers like α-smooth muscle actin (SMA), vimentin, and SM22α." (PMID 26904289, 2016). "In addition, cerebral samples from SAH patients with aneurysm demonstrated the existence of many NSC markers, such as Nestin, vimentin, SOX-2, Musashi-1, and Musashi-2, which possibly contribute to the neural regeneration and functional recovery after aneurysm rupture." (PMID 28133486, 2017).
bacterial meningitis (6 papers, 2012 to 2023). Inflammation of the membranes surrounding the brain and spinal cord due to a bacterial infection. "In conclusion, these results reveal a novel receptor-ligand interaction that enhances adhesion to and penetration of the BBB to cause bacterial meningitis in the S. suis infection and highlight the importance of vimentin in host-pathogen interactions." (PMID 35853077, 2022). "This is the first in vivo study to demonstrate how vimentin and related factors contributed to the pathogenic triad of bacterial meningitis." (PMID 27657497, 2016). "Using the vimentin knockout (KO) mice in this study, we find that, vimentin is the key regulator of the pathogenic triad of bacterial meningitis, IbeA-induced E. coli K1 invasion, NF-κB activation and PMN transmigration across the BBB." (PMID 27657497, 2016). "Thus, the InlF-vimentin interaction represents a novel step in the pathogenesis of L. monocytogenes leading to bacterial meningitis." (PMID 29487235, 2018). "Further dissecting the vimentin- α7 nAChR axis may lead to the discovery and development of novel therapeutic interventions against the triad features of bacterial meningitis." (PMID 27657497, 2016). "IbeA-induced signaling through its binding proteins vimentin as well as PSF is required for meningitic E. coli K1 penetration across the blood-brain barrier (BBB), which is one of the hallmarks of bacterial meningitis." (PMID 22536447, 2012). "IbeA-induced NF-κB signaling through its primary receptor vimentin as well as its co-receptor PSF is required for meningitic E. coli K1 penetration and leukocyte transmigration across the blood-brain barrier (BBB), which are the hallmarks of bacterial meningitis." (PMID 22536447, 2012). "Cooperative contributions of vimentin and PSF to IbeA-induced cytoplasmic activation and nuclear translocation of NF-κB may represent a new paradigm in pathogen-induced signal transduction and lead to the development of novel strategies for the prevention and treatment of bacterial meningitis." (PMID 22536447, 2012). "Cooperative contributions of vimentin and PSF to IbeA-induced cytoplasmic activation and nuclear translocation of NF-κB may represent a new paradigm in pathogen-induced signal transduction and lead to the development of novel strategies for prevention and treatment of bacterial meningitis." (PMID 22536447, 2012).
Cerebral ischemia (6 papers, 2016 to 2023). Restriction of arterial blood supply to the brain associated with insufficient oxygenation to support the metabolic requirements of the tissue. "In support of this contention, previous work by others has demonstrated that GFAP/vimentin knockout mice exhibit reduced reactive astrogliosis and significantly enhanced neuronal damage following a cerebral ischemia, suggesting that reactive astrogliosis is neuroprotective after a cerebral ischemia." (PMID 37106821, 2023). "Thus an upregulation of GFAP and vimentin suggests that structure and/or function of the retina has been compromised after 15 minutes of global cerebral ischemia." (PMID 27322388, 2016).
cervical tumor (6 papers, 2010 to 2023). "In this paper, we describe an extremely rare case of a 77-year-old woman with primary malignant cervical tumor displaying biphasic histomorphology with an epithelioid and sarcomatoid part; the latter was immunohistochemistry positive for cytokeratin and vimentin." (PMID 32035484, 2020). "Moreover, knocking down LSD1 in cervical tumor cells restored the expression of E-cadherin and reduced the expression of Vimentin." (PMID 27894088, 2017). "In a clinical setting, one could use a combination of p16, CEA and vimentin in cervical tumours to determine possible site of origin." (PMID 20199664, 2010). "Although the origin of cervical PNET is not clear, the immunohistochemical markers of cervical neoplasms in this case, including CD99, Syn, CD56, and vimentin (partial), were positively expressed, which satisfies the diagnostic criteria of pPNET." (PMID 34006225, 2021).
coronary artery disease (6 papers, 2015 to 2026). "Today it is known that increased serum levels of secretory vimentin are associated with the presence and severity of coronary artery disease; further, vimentin level is an independent determinant of this disease." (PMID 35453578, 2022). "The mean titers of anti-vimentin antibodies calculated in the period between 1 and 5 years post-transplant were significantly increased in patients who had developed transplant-associated coronary artery disease compared with those free from the disease." (PMID 35603145, 2022). "Pre- and post-transplant serum samples from 109 cardiac transplant recipients were tested for anti-vimentin antibodies up to 5 years after transplantation, and the antibody titers were correlated to the development of transplant-associated coronary artery disease." (PMID 35603145, 2022). "The basis of the study was that vimentin is the major protein of anti-endothelial antibodies and the production of anti-vimentin antibodies long term is an independent risk factor for post-transplant coronary artery disease." (PMID 26592904, 2015). "Therefore, by utilizing this ELISA, anti-vimentin antibodies could potentially be used as biomarkers for identifying patients who have a higher risk for developing transplant-associated coronary artery disease." (PMID 35603145, 2022). "Additionally, anti-CCP antibodies targeting citrullinated sarcomeric proteins, namely fibrinogen and vimentin, can lead to heart issues independently of coronary artery disease." (PMID 37763669, 2023).
cutaneous melanoma (6 papers, 2013 to 2022). A primary melanoma arising from atypical melanocytes in the skin. "BLM cells are derived from lung metastasis of cutaneous melanoma, therefore they have already gone through an EMT process, which is associated with an increase in vimentin level." (PMID 29016654, 2017). "All excised tumors were diagnosed as primary cutaneous melanomas with rhabdoid differentiation based on histomorphological findings and immunohistochemistry considering S100, MART-1, SOX-10, HMB-45, vimentin and desmin." (PMID 35645230, 2022). "β1 integrin level was decreased after both types of radiation in uveal melanoma cells, and the level of vimentin increased in BLM, cutaneous melanoma cells." (PMID 29016654, 2017).
dengue virus infection (6 papers, 2012 to 2025). "Vimentin acts as a receptor or coreceptor for various viruses, including dengue, influenza A, SARS-CoV, and SARS-CoV-2, facilitating entry and replication." (PMID 40630640, 2025). "Vimentin is involved in the viral life cycle as an IF to synthesize the cytoskeleton and inhibits dengue virus infection." (PMID 35433510, 2022). "During Dengue virus infection, vimentin interacts with the NS4A protein, and facilitates formation of the replication complex, suggesting that it participates in virus replication." (PMID 26544179, 2015). "The subsequent co-localization study confirmed the co-existence of vimentin, hnRNPs, and dengue NS1 in perinuclear regions, suggesting their roles associated with assembling in perinucleus upon dengue virus infection." (PMID 23162545, 2012). "Therefore it was postulated that dengue virus uses more than one receptor to infect cells and that perhaps β3 integrin and superficial vimentin cooperate in mediating dengue virus infection." (PMID 28882889, 2017). "Therefore, studies on vimentin phosphorylation could help to overcome the limitation of traditional drugs and treat dengue fever through another mechanism." (PMID 35433510, 2022). "Indeed, vimentin has been shown to play important roles in virus attachment and entry of severe acute respiratory syndrome-related coronavirus (SARS-CoV), dengue and encephalitis viruses, among others." (PMID 32630064, 2020).
gallbladder carcinoma (6 papers, 2013 to 2024). "In gallbladder carcinoma, E-cadherin and vimentin protein levels were affected by miR-30a-5p depletion, and these influences were partly weakened by E2F7 suppression." (PMID 33637098, 2021). "LncRNA KIAA0125 also has been found that it could promote the progress of gallbladder carcinoma through modulating the expression of β-catenin and Vimentin." (PMID 30061172, 2018). "In general, primary gallbladder carcinoma consistently shows positive staining for CK7, EMA, and CEA, but is negative for CA9 and vimentin." (PMID 32347406, 2020).
gastric adenocarcinoma (6 papers, 2016 to 2022). "In the present study, the impact of metformin and VIMENTIN-specific siRNA (vim-siRNA) on VIMENTIN downregulation and cell motility were compared with each other in human gastric adenocarcinoma cell line." (PMID 35178358, 2021). "Moreover VIM gene was found to be heavily methylated in well-differentiated gastric adenocarcinoma." (PMID 31653136, 2019). "Results showed that this cotreatment modulated numerous critical proteins, such as EGFR/HER2/HER3, Kras/ERK/Vimentin, and mTOR/HIF1-α/HK2/LDHA pathways of gastric adenocarcinoma AGS cells." (PMID 36145507, 2022).